CD4 (CD4 molecule)
Diseases named in the same sentence as CD4 in open-access papers (continued):
Sharing a sentence is not in itself a finding about the gene and the disease.
sarcopenia (continued). "Regarding CD4 T-cell count, most patients with counts > 200 cells/mm3 were not at risk for sarcopenia." (PMID 39752996, 2025). "In addition, categorical analysis of high vs low muscle attenuation by sex also demonstrated a trend toward association between sarcopenia and TEMRA CD4 T cells (p = 0.076)." (PMID 40144851, 2025). "The protective causal effects of EM DN (CD4- CD8-) %DN on sarcopenia were also possible via SIRT2, due to the negative causal association of SIRT2 with AWCU10." (PMID 39229276, 2024). "CD4 + FoxP3 + Tregs infiltrate impaired skeletal muscle, which suggested that sarcopenia may lead to tumor immune escape." (PMID 35923193, 2022). "Both definitions of sarcopenia and severe sarcopenia were associated with older age, lower level of education, lack of employment, lower CD4 count, higher Charlson's comorbidity index, multimorbidity and polypharmacy." (PMID 36176015, 2022). "Among PLWH, sarcopenia was associated with demographic and HIV‐related factors, including age, sex, education, employment status, smoking, alcohol use, longer duration of HIV infection, CD4 count and longer exposure to anti‐retroviral therapy." (PMID 36176015, 2022). "Additionally, CD4+FoxP3+ Tregs infiltrate damaged skeletal muscles, suggesting that sarcopenia may play an important role in tumor immune escape." (PMID 36969820, 2023). "Studies have shown that CD3+ T cells, including both CD4+ and CD8+ subsets, progressively decline with advancing age, underscoring age‐related T cell impairment in sarcopenia." (PMID 41357670, 2025). "Specific subsets of lymphocytes, such as CD4 + CD28 null T cells, have been found to be negatively correlated with muscle mass, suggesting their involvement in muscle degradation in sarcopenia." (PMID 40904783, 2025). "The multivariate Cox regression analysis showed that pathological tumour–node–metastasis stage, CD19+ cells, sarcopenia and CD3+/CD4+ cell–myosteatosis were identified as independent prognostic factors for PFS and OS in patients." (PMID 38894548, 2024). "In this study, higher EM DN (CD4- CD8-) %DN was proven to be causally associated with higher levels of IL-17A, higher scores of AALM, lower levels of SIRT2, LIF-R, and DNER, and lower risk of poor hand grip strength (EWGSOP), which might be protective causal factors of sarcopenia." (PMID 39229276, 2024). "The optimal models for PFS and OS encompassed CA724, pTNM stage, CD19+ cells, VAT, sarcopenia and CD3+/CD4+ cell–myosteatosis." (PMID 38894548, 2024). "This study determined that independent prognostic factors for PFS and OS were CD19+ cells, pTNM stage, sarcopenia and CD3+/CD4+ cell–myosteatosis." (PMID 38894548, 2024). "Moreover, immunosenescent T cell phenotypes, such as CD4+CD28null T cells, exhibit a negative correlation with skeletal muscle mass index in patients with sarcopenia." (PMID 41357670, 2025). "In addition, CD4+ TILs also tended to be lower in the sarcopenia group than in the non-sarcopenia group (66.7% versus 45.5%, P = 0.16)." (PMID 37191859, 2023). "Third, we did not measure CD4 + (e.g. CD4 + nadir, current CD4+, CD4+/CD8 ratio+) among the participants, which is important to advance the understanding of immune function and development of sarcopenia in PLWH." (PMID 35142082, 2022). "Research has indicated that a specific subset of CD4+ T helper 1 cells, characterized by the absence of CD28 (CD4+CD28null T cells), showed a negative correlation with muscle mass index in patients with sarcopenia." (PMID 39764565, 2025).
sarcopenia (continued). "The results showed a strong positive correlation (p < 0.01) between NFKBIA and effector.Memory.CD4.T.cell and memory.B.cell, while ZFP36 had a strong negative correlation with both eosinophils and type 2.T.helper.cell cells (p < 0.01) in the sarcopenia datasets." (PMID 38962732, 2024).
unstable angina (25 papers, 2005 to 2025). "An increased risk for angina pectoris, myocardial infarction, and cardiac death has also been described for patients with rheumatoid vasculitis and patients with chronic kidney disease depending on their level of CD4+CD28− T cells." (PMID 25834833, 2015). "Also peripheral blood mononuclear cells cocultured with TNF-α showed downregulation of the CD28 costimulatory receptor, and high levels of TNF-α are associated with higher levels of CD4+CD28− T cells in patients with unstable angina, supporting the findings of the in vitro studies." (PMID 25834833, 2015). "Specifically, high proportions of CD4+ CD28- T cells have been reported in individuals with unstable angina, within unstable plaques, and in persons with recurrent coronary events." (PMID 36865544, 2023). "CD4+CD28− T cells were first identified in the plaques of patients with unstable angina but since then, expansions of these cells have been reported in a range of cardiovascular (CV) conditions." (PMID 28303136, 2017). "As previously reported, frequencies of CD4+CD28null T cells were low in individuals with stable angina (median: 0.7%)." (PMID 16207339, 2005). "A retrospective clinical study found that unstable angina patients treated with statins for at least 1 month had fewer CD4+CD28null T cells than those given standard anti-ischemic therapy without statins, an effect that correlated well with plasma C-reactive protein (CRP) levels." (PMID 38963798, 2024). "Indeed, a seminal investigation showing the efficacy of statin use in reducing recurrent ischemic events in unstable angina patients found that the benefits of statin therapy were highly dependent on the presence of an initial CD4+CD28null T-cell expansion." (PMID 38963798, 2024). "In addition, our previous study demonstrated that miRNA-155 was differentially expressed in circulating blood CD4+ T lymphocytes in patients with unstable angina and was involved in the regulation of differentiation and the activation and function of CD4+ T lymphocytes and its subsets." (PMID 30046360, 2018). "CD4+CD28− T cells occur frequently in patients with unstable angina but are rare in stable angina and healthy controls, leading to the speculation that these cells are involved in the development of cardiovascular events and apoptotic effects on vascular wall cells." (PMID 25834833, 2015). "Patients with unstable angina showed higher numbers of CD4+ and CD8+ T-cells producing IFN-γ than patients with stable angina." (PMID 38256155, 2024). "The average Treg abundance, typically defined as CD4+CD25+CD127low by flow cytometry, was 4.7% in normal, but decreased to 3.2% in CAD or unstable angina (30.3% reduction)." (PMID 34479557, 2021). "Reportedly, plaques in unstable angina patients present clonally expanded peripheral blood CD4 T cells lacking CD28 expression (CD4+CD28null), which are also increased in patients with RA." (PMID 38627782, 2024). "Frequencies of proinflammatory CD4+CD28null T cells were not significantly different between patients with unstable angina (without RA) and those with RA and CAD." (PMID 16207339, 2005). "In contrast, individuals with unstable coronary syndromes (without RA) had an almost sevenfold expansion of CD4+CD28null T cells (median: 4.8%, P = 0.009 for stable vs unstable angina comparison)." (PMID 16207339, 2005). "Remarkably, the reduction of both CD4 + CD69 + and Treg CD69 + T cells was observed in NSTEMI and STEMI patients but not in stable angina." (PMID 35354890, 2022). "In ATS plaques that form in unstable angina patients, CD4+ cells without the co-stimulatory receptor CD28 (CD4+ CD28null T cells) are formed and expanded in the peripheral blood of these patients as well as a subset of RA patients." (PMID 35206926, 2022). "Early observations showed a significant higher percentage of circulating CD4+CD28null T cells and perforin-expressing CD4+ T cells in non-ESRD patients with unstable angina." (PMID 24288592, 2013).
abscess (24 papers, 2009 to 2025). An inflammatory process characterized by the accumulation of pus within a newly formed tissue cavity which is the result of a bacterial, fungal, or parasitic infection or the presence of a foreign body. "To lend further evidence to the premise that T cells are crucial for S. aureus abscess formation, we used CD4 T cell deficient mice." (PMID 20949105, 2010). "This equilibrium is disrupted in individuals with low CD4+ T-lymphocyte counts, leading to uncontrolled protozoan proliferation and abscess formation, which are typically symptomatic or identifiable by brain imaging." (PMID 39871838, 2024). "A 40-year-old male with a history of human immunodeficiency virus (HIV) (CD4 absolute count 57 cells/uL) presented to the Emergency Department complaining of large, swollen abscesses on his face, right hand, and feet." (PMID 39077262, 2024). "A previous study reported that CD4+ T cells mediated abscess formation in intra-abdominal sepsis in an IL-17A-dependent manner." (PMID 32849528, 2020). "ZPS-activated CD4 T cells produce interleukin-10 (IL-10), which is essential to prevent abscess formation and other unchecked inflammatory responses." (PMID 28144234, 2016). "Intra-abdominal ZPS challenge induces the differentiation of proinflammatory CD4 T cells resulting in abscess formation." (PMID 21234388, 2010). "As an alternative approach, clonotype mapping of abscess-inducing CD4 T cells from mouse models shows the existence of ZPS-specific clones." (PMID 21234388, 2010). "CD4 T cells activated by purified wt WTA were sufficient to provoke abscesses when injected s.c. into the flanks of healthy mice." (PMID 20949105, 2010). "This recruitment of CD4 T cells together with other innate cells results in the generation of intra-abdominal abscess, a defensive mechanism of the body to contain the infection." (PMID 21234388, 2010). "These in vivo data clearly demonstrate the link between WTA dependent T cell activation and the modulation of abscess formation by activated CD4 T cells." (PMID 20949105, 2010). "We conclude that Sp1 attracts CD8+C28− T cells into the peritoneal cavity that modulate CD4+ T cell-dependent abscess formation." (PMID 19779562, 2009). "Although there is a small number of Ts cells participating in abscess formation, their depletion results in a significant enlargement of the abscess size, suggesting that they have an important role in their ability to regulate CD4+ T cell responses." (PMID 19779562, 2009). "A model ZPS antigen of commensal bacteria Sp1 induces CD8+CD28− T lymphocytes which exhibit a suppressive function on CD4+ T cells in intraperitoneal abscess formation and in an allogeneic CD4+ T cell proliferation assay." (PMID 19779562, 2009). "To study CD8+ T cell immunity to ZPS, we first employed a well characterized experimental model of CD4+ T cell-dependent immune response, which is the mouse model of Sp1-mediated abscess formation." (PMID 19779562, 2009). "Another study has proven that Bacteroides fragilis-derived polysaccharides (PSAs) may stimulate CD4+ T cells, and these cells can produce IL-10, which may inhibit the occurrence of abscesses and other inflammatory reactions." (PMID 39858150, 2025). "Histology showed significant mucosal damage and inflammation characterized by disruption of crypt architecture, crypt branching, crypt abscess formation, marked increase in mucosal thickness, and lymphocyte infiltration in the epithelial and submucosal layers in the CD4-Cre+/TgMettl14FL/FL mice." (PMID 32634481, 2020). "Furthermore, the adoptive transfer of CD4 T cells from mice that were vaccinated with ZPS prevented the induction of intra-abdominal abscesses in the recipients in an IL-2-dependent manner." (PMID 21234388, 2010). "As predicted, WTA provoked abscesses in C57Bl/6 mice, but not in CD4-deficient C57Bl/6 tm1mac mice." (PMID 20949105, 2010).
abscess (continued). "Besides having specific effects on the formation of ZPS-induced abscesses, the IL-10-producing CD4 Treg populations seemed to broadly protect the mucosal immune system from diseases mediated by microbial pathogens, such as H. hepaticus-induced experimental colitis." (PMID 21234388, 2010). "Curley and colleagues found a significant reduction in the proportion of CD4+ T cells in SAP with local complications, such as abscess, necrosis or pseudocyst, compared with the mild form." (PMID 26287969, 2015). "CD4-dominant HS patients exhibited a significantly greater involvement of the mons pubis (62.5% vs. 28.6%, p = 0.023) compared to CD8-dominant patients, who demonstrated a significantly higher number of abscesses (p = 0.027)." (PMID 40981339, 2025). "However, only very few single apoptotic DCs (CD11c+TUNEL+) were found in Yersinia-induced abscesses in the spleen of infected mice, and total numbers of 7-AAD+ CD4+ and CD8α+ DCs were unaltered upon Ye infection and in PBS-treated control mice." (PMID 21124820, 2010). "The activation of CD4 T cells is required for ZPS-mediated intra-abdominal abscess induction because mice lacking CD4 T cells failed to develop abscesses." (PMID 21234388, 2010). "However, the same immunogen, when subcutaneously administered without an adjuvant, induces the activation of immunosuppressive CD4 and CD8 Tregs, both secrete immunosuppressive IL-10 molecules and prevent intra-abdominal abscess formation." (PMID 21234388, 2010). "In the absence of IL-6, the abscess formation is inhibited, which suggests that the recruitment, activation, and survival of CD4 T cells are required for the induction of abscess formations." (PMID 21234388, 2010). "In contrast, mSp1 without the positive charged substituent and therefore resembling a common negatively charged polysaccharide not only fails to induce CD4+ T cell-dependent abscesses but also CD8+CD28− T cells in the peritoneum and in the spleen." (PMID 19779562, 2009). "CD4+ T cell-dependency of this immune response is confirmed, as CD4+ T cell depletion leads to significant inhibition of abscess formation (no abscesses observed)." (PMID 19779562, 2009). "CD4−/− mice similarly injected with WTA failed to develop abscesses." (PMID 20949105, 2010). "However, it is interesting to note that both the CD4 and CD8 T cells are recruited to the abscess wall upon intra-abdominal ZPS administration, but the induction of immunosuppressive CD4 and CD8 phenotypes were inhibited in the peritoneum during the abscess development." (PMID 21234388, 2010). "Moreover, CD4−/− mice injected with WTA failed to develop abscesses." (PMID 20949105, 2010).
aneurysm (24 papers, 2007 to 2025). Bulging or ballooning in an area of an artery secondary to arterial wall weakening. "Accumulating evidence from murine models has established that genetic ablation of CD4+ T cells confers protection against aneurysm development, mechanistically linked to attenuated interferon‐gamma (IFN‐γ) signalling pathways." (PMID 41208012, 2025). "Activated macrophage and pro-inflammatory CD4 T-cell infiltration has been linked to aneurysm formation and rupture in murine models." (PMID 38275364, 2023). "To further characterize the transition state linked to CD4 and CD8 T cells in aneurysm groups, we inferred the movement trajectories of CD4 and CD8 T cells in the TAA and AAA groups, respectively." (PMID 36703732, 2022). "Replacement of IFN-γ by reinfusion of competent splenocytes from wild-type mice promoted aneurysm formation in these CD4−/− animals, underlining the crucial role of IFN-γ in AAA disease." (PMID 31989839, 2020). "Rag1−/− mice are resistant to aneurysm formation in the CaCl2 model; however, when supplemented with human CD4+ cells, they became susceptible to AAA formation." (PMID 32968712, 2020). "Additionally, deficiency of CD4 Th17 cell signaling, a process driven by IL-1β, is associated with reduced aortic macrophage infiltration and attenuated aneurysm formation in murine models." (PMID 38275364, 2023). "Furthermore, deficiency of CD4+ T cells in a calcium chloride (CaCl2)-induced murine aneurysm model was shown to be related to lower expression of MMP and inhibition of aneurysm development." (PMID 31989839, 2020). "Deficiency of either CD4 or INF-γ prevents CaCl2-induced aneurysm." (PMID 27659201, 2016). "IL21R showed positive correlations with activated CD4 T cells and activated B cells, highlighting its potential role in the immune landscape of aneurysms." (PMID 40313967, 2025). "Finally, through our analysis of immune cell infiltration, we hope to further verify the infiltration of T cell CD4, macrophage lineage in ruptured aneurysms and the potential mechanism between them and aneurysm rupture in subsequent experiments." (PMID 38518032, 2024). "These lines of evidence indicated that CD4+ T cells are crucial to the rupture of aneurysms." (PMID 30258282, 2018). "However, the aneurysm could be reconstituted in CD4−/− mice with INF-γ injections, suggesting an essential role of T lymphocytes in AAA formation." (PMID 27659201, 2016). "Depletion of CD4+ T cells or IFN-γ in mice prevented aneurysm formation, and reinfusion of IFN-γ in CD4–/ – mice or CD4+ T cells in IFN-γ null mice reconstituted aneurysms and orchestrated matrix remodeling." (PMID 38036736, 2023). "Several studies reported that Th1 cells, as the predominant type of CD4+ T cells in TAA, positively correlated with aortic expansion in aneurysm patients." (PMID 35463756, 2022). "Except for the CD4 GAMB subset, other subsets were shared across aneurysm and normal groups, albeit in variable proportions possibly because of the low cell numbers in the normal group." (PMID 36703732, 2022). "We also expand on these earlier findings by demonstrating that the majority of CD4+ and CD8+ T cells present within the aneurysm positively express CD69 as well as showing expression of other activation markers including HLA-DR+ and CCR5." (PMID 31552015, 2019). "In all patients of the first group (patients with a high activity of the inflammatory process in the aneurysm wall), in the lumen of the vasa vasorum vein and among the attached cells, there were CD3, CD4, and CD8 T cells (usually one or two T cells were attached in one vein of the vasa vasorum)." (PMID 37240684, 2023). "The immunohistochemical staining was used to analyze the infiltration of pro-inflammatory (CD68) and anti-inflammatory macrophages (CD163), T helper (CD4) and T killer cells (CD8), and B (CD79a) and plasma cells (CD138) in all three layers of aneurysms of both groups." (PMID 34656077, 2022).
aneurysm (continued). "Early studies showed that administration of recombinant IFNγ into mice lacking CD4+ T cells promotes aneurysm development." (PMID 36275758, 2022). "In addition, the presence of CD4+ and CD20+ lymphocytes increased in parallel with both aneurysm rupture and the presence of vascular and lymphatic neovessels: unruptured sIAs without neovessels exhibited virtually no lymphocytes, whereas those with neovessels showed low densities." (PMID 40498464, 2025). "However, the definite roles of different CD4 + T lymphocytes subtypes in AAA pathogenesis and expansion are conflicting due to the differences in technical measurement, animal models, and the disease state at which aneurysm samples are obtained." (PMID 34637689, 2021).